PDE3A (phosphodiesterase 3A)
Description:
Cyclic nucleotide phosphodiesterase with specificity for the second messengers cAMP and cGMP, which are key regulators of many important physiological processes. Also has activity toward cUMP. Independently of its catalytic activity it is part of an E2/17beta-estradiol-induced pro-apoptotic signaling pathway. E2 stabilizes the PDE3A/SLFN12 complex in the cytosol, promoting the dephosphorylation of SLFN12 and activating its pro-apoptotic ribosomal RNA/rRNA ribonuclease activity. This apoptotic pathway might be relevant in tissues with high concentration of E2 and be for instance involved in placenta remodeling.
Synonyms: CGI-PDE A; cGI-PDE; CGI-PDE-A; HTNB
Tractability: Small molecule: an approved drug acts on it; a structure with a bound ligand is known; a high-quality ligand is known; it belongs to a druggable protein family. Antibody: UniProt predicts a signal peptide or a membrane-spanning region; the Human Protein Atlas places it where antibodies can reach. PROTAC: UniProt records ubiquitination sites on it; ubiquitination databases record sites on it; a small molecule that binds it is known.
Target class: Phosphodiesterase 3A; Enzyme; Phosphodiesterase; Phosphodiesterase 3
Safety:
Unwanted effects reported when the protein is acted on. In parentheses: how it was acted on, where the effect was seen, and who reports it.
decreased blood pressure (Lynch et al. (2017): inhibition, acute dosing, cardiovascular, blood; Bowes et al. (2012): inhibition, cardiovascular system)
increased cardiac contractility (Bowes et al. (2012): inhibition, cardiovascular system; Lynch et al. (2017): inhibition, acute dosing, cardiovascular, blood)
increased heart rate (Lynch et al. (2017): inhibition, acute dosing, cardiovascular, blood; Bowes et al. (2012): inhibition, cardiovascular system)
ventricular arrhythmia (Lynch et al. (2017): inhibition, acute dosing, cardiovascular, blood; Bowes et al. (2012): inhibition, cardiovascular system)
decreased female fertility (inhibition, acute dosing; cardiovascular, blood; source: Lynch et al. (2017))
decreased platelet aggregation (inhibition, acute dosing; cardiovascular, blood; source: Lynch et al. (2017))
decreased platelets (inhibition, acute dosing; cardiovascular, blood; source: Lynch et al. (2017))
hypotension (inhibition; cardiovascular system; source: Urban et al. (2012))
increased mortality in heart failure patients (inhibition, chronic dosing; cardiovascular system; source: Urban et al. (2012))
tachycardia (inhibition; cardiovascular system; source: Urban et al. (2012))
thrombocytopaenia (inhibition; cardiovascular system; source: Bowes et al. (2012))
thrombocytopenia (inhibition, chronic dosing; cardiovascular system; source: Urban et al. (2012))
ventricular arrhythmias (inhibition; cardiovascular system; source: Urban et al. (2012))
opioid-induced nausea and vomiting (source: ClinPGx)
Gene: Protein-coding gene on chromosome 12 (20,368,537 to 20,688,583, forward strand). Ensembl gene ENSG00000172572.
Subcellular location: Membrane; Cytoplasm, cytosol
Subcellular location (Human Protein Atlas): Plasma membrane
Pathways (Reactome):
Signal Transduction: G alpha (s) signalling events
Gene Ontology:
Molecular function: 3',5'-cGMP-inhibited cyclic-nucleotide phosphodiesterase activity; 3',5'-cyclic-AMP phosphodiesterase activity; 3',5'-cyclic-GMP phosphodiesterase activity; 3',5'-cyclic-nucleotide phosphodiesterase activity; estrogen binding; nuclear estrogen receptor activity; protein binding; phosphoric diester hydrolase activity
Biological process: apoptotic signaling pathway; cellular response to cGMP; cellular response to transforming growth factor beta stimulus; negative regulation of adenylate cyclase-activating G protein-coupled receptor signaling pathway; negative regulation of vascular permeability; positive regulation of vascular permeability; regulation of ribonuclease activity; G protein-coupled receptor signaling pathway; lipid metabolic process; negative regulation of cAMP/PKA signal transduction; negative regulation of apoptotic process; nuclear receptor-mediated steroid hormone signaling pathway; oocyte maturation; signal transduction
Cellular component: cytosol; membrane
Genetic constraint (gnomAD): Loss-of-function variants: 29 observed, 51.84 expected, observed/expected ratio (o/e) 0.56, 90% interval 0.42 to 0.76. The synonymous counts are far from expectation, so gnomAD's model fits this gene poorly and the ratio says little. Missense variants: 1,071 observed, 1,016.5 expected, observed/expected ratio (o/e) 1.05, 90% interval 1 to 1.11. Synonymous variants: 522 observed, 436.09 expected, observed/expected ratio (o/e) 1.2, 90% interval 1.11 to 1.29.
Homologues: Orthologues: chimpanzee PDE3A (99% identical), macaque PDE3A (99% identical), pig PDE3A (93% identical), dog PDE3A (90% identical), rabbit PDE3A (89% identical), guinea pig PDE3A (87% identical), rat Pde3a (84% identical), mouse Pde3a (84% identical), zebrafish pde3a (56% identical), tropical clawed frog PDE3A (50% identical), Caenorhabditis elegans pde-3 (23% identical), Drosophila melanogaster Pde11 (11% identical), and 2 more. Paralogues in human: PDE3B (42% identical), PDE1C (15% identical), PDE4A (15% identical), PDE1A (14% identical), PDE4D (14% identical), PDE11A (13% identical), PDE4B (13% identical), PDE8B (13% identical), PDE4C (13% identical), PDE1B (13% identical), PDE2A (13% identical), PDE6C (13% identical), and 8 more.
Diseases named in the same sentence as PDE3A in open-access papers:
PDE3A is named in the same sentence as 90 diseases in open-access papers, as found by Europe PMC text mining. Sharing a sentence is not in itself a finding about the gene and the disease. The quoted sentences say what the papers report.
Hypertension (21 papers, 2017 to 2025). The presence of chronic increased pressure in the systemic arterial system. "This includes using gene editing technologies to precisely target PDE3A mutations or modulate immune responses to alleviate hypertension." (PMID 40079010, 2025). "One notable development is the identification of phosphodiesterase 3A (PDE3A) gene mutations that enhance enzyme activity and are associated with hypertension with brachydactyly (HTNB)." (PMID 40079010, 2025). "In conclusion, while PDE3A mutations represent a promising therapeutic target for hypertension, much work remains to be done." (PMID 40079010, 2025). "A primary challenge is the need for more in vivo models to confirm the involvement of mutated PDE3A in hypertension development." (PMID 40079010, 2025). "Of note, missense mutations in PDE3A have been associated with an autosomal dominant form of hypertension." (PMID 38494474, 2024). "A CRISPR-Cas9-generated rat model, with a 9 bp deletion within the hotspot analogous to the novel mutation of the human PDE3A gene, recapitulates arterial hypertension with brachydactyly, demonstrating that mutant PDE3A causes arterial hypertension." (PMID 36895064, 2023). "All reported variants in PDE3A gene, which causes hypertension and brachydactyly syndrome, were missense variants, and blood pressure, fingers and toes were normal." (PMID 36071901, 2022). "Recent studies have demonstrated that six missense mutations of PDE3A in six unrelated families with Mendelian hypertension exhibit severe salt-independent but age-dependent hypertension." (PMID 32731518, 2020). "Hypertension with brachydactyly Type E is associated with a missense mutation of the PDE3A gene, encoding for phosphodiesterase 3A." (PMID 28587112, 2017). "Hypertension with brachydactyly is caused by a mutation in the PDE3A gene which encodes phosphodiesterase 3A." (PMID 29404309, 2017). "Understanding how PDE3A mutations influence T cell activation and proliferation could reveal novel gene-targeted therapies for hypertension." (PMID 40079010, 2025). "Such integrated research approaches could uncover novel signaling pathways and mechanisms through which PDE3A mutations influence vascular changes and contribute to hypertension." (PMID 40079010, 2025). "Notably, a recent study has shown that PDE3A mutations cause Mendelian hypertension and brachydactyly type E." (PMID 35345488, 2022). "PDE3A was previously associated with Mendelian hypertension." (PMID 28842720, 2017). "Gain-of-function PDE3A mutations cause hypertension with brachydactyly (HTNB; Bilingturan syndrome), a rare disease with harmless brachydactyly but progressive, severe hypertension that resembles essential hypertension." (PMID 40497949, 2025). "For example, while overexpression of PDE3A in smooth muscle cells leads to increased vascular resistance and hypertension, the interaction between these genetic alterations and immune cells—especially T cell subsets—remains poorly understood." (PMID 40079010, 2025). "In summary, the present study showed that DNA methylation in the promoters of PRDM6, HDAC9, IGFBP3, LRRC10B, SYT7, PDE3A, TBX2 and C17orf82 genes were significantly associated with BP or hypertension." (PMID 35087571, 2021). "While advanced technologies like CRISPR/Cas9 have been used to generate PDE3A-mutant animal models, these models do not yet fully capture the immune dynamics of human hypertension." (PMID 40079010, 2025). "A recent study shows that the hypertension-related gain-of-function mutations of PDE3A do not affect overall adrenergic stimulation and cAMP levels but reduce PLB phosphorylation, which leads to adaptive change in Ca2+ cycling and protects against hypertension-induced cardiac damage in the hearts." (PMID 37971403, 2024).
breast carcinoma (5 papers, 2020 to 2025). "Breast tumor cells were found sensitive to PDE3A inhibitors, and expression of PDE3A was negatively correlated with breast cancer prognosis." (PMID 36159573, 2022). "Inhibition of PDE3A with cilostazol could reduce metastasis and suppress tumor growth in xenograft breast cancer models." (PMID 41179677, 2025). "In addition, PDE3A was shown to be able to suppress cAMP/PKA and induce NFκB signaling pathway, causing expression of the stem cell marker OCT4 and cancer stemness in breast cancer." (PMID 41179677, 2025). "Similarly, PDE3A has been shown to drive stem cell-like properties and metastasis in breast cancer." (PMID 40961924, 2025). "In addition, we showed that the PDE3A gene maintains cancer cell stemness and may therefore serve as a target in breast cancer therapy." (PMID 33500726, 2021). "Moreover, ICAM3, CCL16, PDE3A, PRTN3, TRAF6, BCAR1, IL-1α, IL-1β, NFκB1, SOX2 and OCT4 decreases the protein expression as indicated by immunofluorescence staining in the ibuprofen-treated MDA-MB-231 breast cancer cells versus the control." (PMID 32528119, 2020).
diabetes (5 papers, 2015 to 2021). "Similar results were obtained in studies carried out in an animal model (Mt3+/+ mice) with STZ induced diabetes, where PDE3A was shown to be implicated in apoptosis of pancreatic islet cells in these animals, and the use of cilostazol alleviated diabetes." (PMID 33153226, 2020).
Stroke (5 papers, 2020 to 2023). Sudden impairment of blood flow to a part of the brain due to occlusion or rupture of an artery to the brain. "Genetic variation in PDE3A influences risk of stroke through altered endothelial function, as measured by flow-mediated dilatation." (PMID 31865795, 2020). "Nevertheless, the fact that the same PDE3A locus has a subsequent influence on stroke risk suggests that the changes that occur in adolescence have a lasting impact on the vasculature and subsequent pathological processes." (PMID 31865795, 2020). "The association with variants in PDE3A was consistent across all stroke subtypes, which are presumed to have distinct etiologies." (PMID 31865795, 2020). "With regard to DMR findings, out of 149 DMRs identified, 2 DMRs were located in genes previously associated with stroke in a multi-ancestry GWAS: FBN2 and PDE3A genes." (PMID 37370144, 2023). "Of these, four (PDE4D, PDE3A, PDE3B, PDE6B) were ranked in the top 1% by the exome method for stroke." (PMID 37492104, 2023).
brachydactyly type E (4 papers, 2017 to 2022). Brachydactyly type E (BDE) is a congenital malformation of the digits characterized by variable shortening of the metacarpals with more or less normal length phalanges, although the terminal phalanges are often short. "Autosomal hypertension with type E brachydactyly is not related to salt reabsorption but due to mutation in the PDE3A gene resulting in enhanced activity of PDE3A leading to increased neointimal proliferation and remodelling of the arteries and neurovascular structures." (PMID 32389342, 2020).
gastrointestinal stromal tumor (3 papers, 2017 to 2025). "Phosphodiesterase 3A (PDE3A) is an emerging therapy target in various cancers with high expression, as in the majority of gastrointestinal stromal tumors (GISTs)." (PMID 40527986, 2025). "However, PDE3A expression and function during gut development and in ICC-derived gastrointestinal stromal tumors (GIST) remained unknown." (PMID 28454120, 2017).
glioblastoma (3 papers, 2021 to 2025). The most malignant astrocytic tumor (WHO grade IV). "Based on previous work in solid tumors such as glioblastoma, only PDE3A and SLFN12 are considered as biomarkers for treatment with velcrins." (PMID 41150877, 2025). "In summary, we demonstrated that velcrins have anti-proliferative effects in a subset of glioblastoma cell lines and neurosphere models and validated a correlation between PDE3A expression and response to velcrin treatment." (PMID 39166256, 2024). "Lastly, we observed in vivo sensitivity to 2 velcrin compounds in subcutaneous glioblastoma PDX models with high PDE3A and SLFN12 expression." (PMID 39166256, 2024). "This library was expressed in PDE3A-knockout GB1 glioblastoma cells and assessed for survival in the presence of dimethyl sulfoxide (DMSO), 100 nM DNMDP, or 100 nM trequinsin." (PMID 34272366, 2021). "To validate the response to velcrin treatment in biomarker-positive glioblastoma cell lines and to determine whether the response is dependent on PDE3A, we tested velcrin sensitivity in GB1 cells and GB1 cells where PDE3A was ablated using CRISPR-Cas9 (GB1 PDE3A KO)." (PMID 39166256, 2024). "Based on the results presented in this work, 50% of tested cell lines were velcrin-sensitive, but only 3% of glioblastoma neurospheres were predicted to be sensitive (including BT423, which has similar PDE3A expression levels to BT288L)." (PMID 39166256, 2024). "Taken together, our work identifies velcrins as a novel therapeutic class with promising preclinical activity against glioblastomas with elevated SLFN12 and PDE3A expression." (PMID 39166256, 2024). "PDE3A and SLFN12 expression levels were measured in glioblastoma cell lines, the Cancer Genome Atlas (TCGA) tumor samples, and tumor neurospheres." (PMID 39166256, 2024). "Tumors with the highest PDE3A and SLFN12 expression levels include IDH wild-type low-grade gliomas and glioblastomas." (PMID 39166256, 2024). "Additionally, we demonstrate the preclinical efficacy of BAY 2666605 and BRD3800 in glioblastomas with high expression of PDE3A and SLFN12 in vitro and in vivo, in both cellular and patient-derived glioblastoma models." (PMID 39166256, 2024). "Velcrin treatment led to a significant reduction in nascent polypeptide formation in velcrin-sensitive glioblastoma cell lines GB1, DBTRG-05MG, and NP5, but not in GB1 PDE3A KO cells." (PMID 39166256, 2024).
ischemic stroke (3 papers, 2017 to 2022). A stroke disorder caused by obstruction of blood flow to the brain, due to thrombotic (local blood clot formation) or embolic (due to a blood clot or other material traveling from another site) event. "We conclude that a genetic variant in PDE3A influences endothelial function in early life and leads to increased risk of ischemic stroke." (PMID 31865795, 2020). "Colocalization analyses indicated that the same genetic variation in PDE3A associated with ischemic stroke is also associated with FMD, thereby showing the shared association is not merely coincidental." (PMID 31865795, 2020). "An interpretation consistent with these data is that the associated genetic locus influences expression of PDE3A in arterial tissues, which leads to altered endothelial function and subsequent risk of ischemic stroke." (PMID 31865795, 2020). "Having established that genetic variation in a single locus in PDE3A is associated with both ischemic stroke and FMD, we sought validation of the association in other cohorts with FMD data." (PMID 31865795, 2020). "We identified a variant in PDE3A (Phosphodiesterase 3A), encoding phosphodiesterase 3A, which was associated with flow-mediated dilatation in adolescents (9–12 years of age; β[SE], 0.38 [0.070]; P=3.8×10−8) and confers risk of ischemic stroke (odds ratio, 1.04 [95% CI, 1.02–1.06]; P=5.2×10−6)." (PMID 31865795, 2020). "In conclusion, we show that genetic variation in phosphodiesterase 3A leads to altered endothelial function in early life, mostly likely via expression of PDE3A, and also leads to increased risk of ischemic stroke, thus elucidating a pathway by which risk of disease is likely conferred." (PMID 31865795, 2020). "Methylation of AMH, C17orf82, HDAC9, IGFBP3, LRRC10B, PDE3A, PRDM6, SYT7 and TBX2 was significantly associated with ischemic stroke." (PMID 35345488, 2022). "According to the results from stage one and stage two, we confirmed that higher methylation levels of 17 targets in AMH, C17orf82, HDAC9, IGFBP3, LRRC10B, PDE3A, PRDM6, SYT7 and TBX2 genes were associated with a lower risk of ischemic stroke." (PMID 35345488, 2022). "Higher methylation levels of 18 targets in AMH, C17orf82, HDAC9, IGFBP3, LRRC10B, PDE3A, PRDM6, SYT7 and TBX2 genes were associated with a lower risk of ischemic stroke." (PMID 35345488, 2022). "We identified a genetic variant in the phosphodiesterase 3A gene that was associated at genome-wide significance with both FMD in early life and ischemic stroke." (PMID 31865795, 2020). "We demonstrate that genetic variation that influences levels of PDE3A influences endothelial function and subsequently, ischemic stroke." (PMID 31865795, 2020). "The PDE3A inhibitor cilostazol has been shown to be clinically effective for secondary prevention of ischemic stroke." (PMID 28583195, 2017). "As an initial step in the development of a therapy that simultaneously treats CMB and ischemic stroke, we hypothesized that inhibition of the PDE3A pathway is protective against CMH development." (PMID 28583195, 2017). "Although it is not possible to determine the exact mechanism by which the PDE3A variant confers risk of ischemic stroke and alters endothelial function without further experimental data, some speculation on potential pathways is warranted." (PMID 31865795, 2020). "However, we cannot rule out other horizontal pathways by which the PDE3A locus also leads to risk of ischemic stroke." (PMID 31865795, 2020). "The results showed that the mean methylation levels of AMH, C17orf82, HDAC9, IGFBP3, LRRC10B, PDE3A, PRDM6, SYT7 and TBX2 were significantly (Wilcoxon's two sample test) lower in ischemic stroke cases than in controls." (PMID 35345488, 2022).
lung adenocarcinoma (3 papers, 2019 to 2024). A carcinoma that arises from the lung and is characterized by the presence of malignant glandular epithelial cells. "Combining SLFN12 with phosphodiesterase 3A (PDE3A) can enhance the lung adenocarcinoma cells sensitivity to DNMDP." (PMID 36090985, 2022). "When coupled with phosphodiesterase 3A (PDE3A), SLFN12 can increase tumor sensitivity to 6-(4-(diethylamino)-3-nitrophenyl)-5-methyl-4,5-dihydropyridazin-3(2H)-one (DNMDP) in lung adenocarcinoma cell lines." (PMID 38832156, 2024).